CD4 (CD4 molecule)
Diseases named in the same sentence as CD4 in open-access papers (continued):
Sharing a sentence is not in itself a finding about the gene and the disease.
hepatitis C (112 papers, 2007 to 2025). "Male sex, age above 35 years, baseline BMI ≥25 kg/m2, triglycerides ≥200 mg/dl, absolute CD4 cell count < 200 cells/mm3 and hepatitis C infection were associated with a higher incidence rate of DM." (PMID 30165821, 2018). "Multivariable linear mixed models with a random intercept and slope adjusted for age, baseline CD4 count, hepatitis C, drug type, RNA (log-scale), risk group and subtype were used to estimate CD4 slopes." (PMID 25397482, 2014). "Hepatitis C incidence was also associated with younger age and higher CD4 cell count nadir." (PMID 28253838, 2017). "Early diagnosis could be improved, reducing the risk for a low CD4 nadir, and coinfection with hepatitis C can be treated." (PMID 22474480, 2012). "TNFSF8 gene expression plays an important role in the defence of immune cells (e.g., CD4 T cells) against Mycobacterium tuberculosis and hepatitis C virus infection." (PMID 40342962, 2025). "After adjusting for ethnicity, history of preterm birth, substance use, concurrent Hepatitis C, CD4 count and viral suppression at delivery, STIBV remains an independent risk factor (OR: 2.09; 95% CI: 1.04 – 4.19; p = .039)." (PMID 40446841, 2025). "For peripheral neuropathy at any visit, HBsAg, hepatitis C serology, CD4 count, CD4 count group, age, BMI and Cotrimoxazole use were included in the multivariate model with gestational age stratum." (PMID 36650479, 2023). "We wanted to analyze any difference in the HCC rate in patients with different CD4 counts, specifically for hepatitis C infection." (PMID 35875299, 2022). "Patients with active hepatitis C had a significant increase incirculating MPs derived from CD4+ as well as CD8+ T cells compared topatients with mild hepatitis C and healthy controls, respectively." (PMID 36555854, 2022). "Other past medical history included untreated hepatitis C. His CD4 count was 90 (11%) cells/mm3 on admission and his HIV viral load VL) was 141,000 copies/ml." (PMID 34589769, 2021). "Dysfunctional expression and activation of the Tim-3 signaling molecule has been linked to CD4+ and CD8+ T cell “exhaustion” in chronic HIV and hepatitis C infection." (PMID 27729904, 2016). "This fact prompted the recommendation of treating hepatitis C before HIV-infection in subjects with high CD4 cell count." (PMID 26848975, 2016). "The association between type of PI (boosted vs. unboosted) and risk of PTB remained significant after adjusting for maternal age, delivery CD4 count, parity, hepatitis C status and ethnicity (aOR 2.17, 95% CI 1.02–4.51)." (PMID 26051165, 2015). "We retrospectively enrolled HIV/HCV-coinfected patients on HIV medications and treated for hepatitis C. CD4 + T cell counts were registered at baseline and after hepatitis C therapy." (PMID 25688301, 2015). "Our results suggested that classical CD4+CD25+ Tregs were significantly enhanced in recurrent hepatitis C and that Tr1 cells were specifically enhanced in severe recurrent hepatitis C." (PMID 24575405, 2014). "The worst CD4+ response was that of IDUs or hepatitis C co-infected individuals, which were very similar." (PMID 24695533, 2014). "Old age, high baseline eGFR, low serum creatinine, low CD4 count, high HIV viral load, concurrent nephrotoxic drugs, hepatitis C infection, and current smoking were also associated with tenofovir-related renal dysfunction." (PMID 21799928, 2011). "Investigators have reported these toxicities more frequently in women with higher baseline CD4 counts (>250 cells/mm3); in pregnancy; and in the presence of pre-existing liver disease (i.e. hepatitis C)." (PMID 20838641, 2010). "Frequencies of tetramer-binding CD4+ T cells were however in a similar range to those observed during acute parvovirus B19 and hepatitis C infections." (PMID 19023425, 2008).
hepatitis C (continued). "This novel tetramer was used to explore the frequency, phenotype and function of hepatitis C virus (HCV)-specific CD4+ T cells in seven patients with acute hepatitis C during the most critical phase of viral elimination or persistence." (PMID 17653276, 2007). "During acute hepatitis C a CD4+ T cell response against this epitope is readily induced in most, if not all, HLA-DR1+ patients." (PMID 17653276, 2007). "The subsequent decline of tetramer+ CD4+ T cells mirrors the kinetics of HCV specific CD8+ T cells in acute hepatitis C that have been studied with HLA class I tetramers." (PMID 17653276, 2007). "After adjusting for ethnicity, history of preterm birth, perinatal substance use, concurrent Hepatitis C, protease inhibitor-based antiretroviral therapies, CD4 count and viral suppression at delivery, STIBV in pregnancy remains an independent risk factor (OR: 2.09; 95% CI: 1.04–4.19; p = .039)." (PMID 40446841, 2025). "Specifically, relative to ACTG 5257 our study population included a greater proportion of patients who had a history of injection drug use (27% versus 7%), were coinfected with hepatitis C (28% versus 7.8%) and with baseline CD4 counts below 350 cells/mm3 (77% versus 8.8%)." (PMID 28399819, 2017). "A potential role for CD4 CTL activity in mediating immunopathology is supported by the observation that two patients who spontaneously cleared Hepatitis C virus (HCV) infection exhibited a significant decrease in perforin-expressing CD4 cells that coincided with viral RNA clearance." (PMID 28167943, 2017). "With the wave of rapidly evolving treatment of hepatitis C, it behooves us to understand its implications in our coinfected population, where the CD4 (+) T cell recovery after the introduction of an effective combined antiretroviral for HIV treatment is unclear in the literature." (PMID 25688301, 2015). "In contrast, three patients with a history of spontaneous HCV clearance, including patient AR1 three years after viral clearance, maintained mean levels of tetramer+ CD4+ T cells of 0.064%+/− 0.03 (range 0.038% to 0.1%) for up to 20 years after acute hepatitis C." (PMID 17653276, 2007). "Thus, it has been shown that older age, a long duration of the HIV infection prior to HAART, coinfection with hepatitis C, and a low CD4 nadir predispose to immunological nonresponse." (PMID 22474480, 2012). "Numerous parameters, such as CD4 cell count, CD4/CD8 ratio, viral load, concurrent hepatitis C infection, and gender differences, have been proposed as potential factors in the serum conversion rate following HAV immunization." (PMID 36644336, 2023). "In patients with mixed hepatitis B and hepatitis C infection, HCC was more prevalent if the CD4 count was below 200 cell/dL." (PMID 35875299, 2022). "We noticed that in patients with hepatitis C, HCC was more prevalent in the extremes of the CD4 count, that is, 2% in those with CD4 below 200 cells/dL and 2.8% in those with a CD4 count above 500 cell/dL." (PMID 35875299, 2022). "We have adjusted for a number of potential covariates commonly known for IDUs (such as IV drug use, injection frequency, and hepatitis C infection) and HIV infection (viral load, CD4 counts, and cART therapy) as well as comorbidities." (PMID 29097998, 2017). "A HCV VLP-based vaccine has the potential to fulfill the requirements of an effective vaccine for hepatitis C. Several approaches have shown that HCV VLPs are immunogenic and capable of eliciting robust CD4+, CD8+, and cross reactive NAb responses." (PMID 29163442, 2017). "In the two patients with acute hepatitis C who were studied only at single time points (AX and AC4), the frequencies of tetramer+ CD4+ T cell were 0.05% and 0.007%, respectively." (PMID 17653276, 2007). "For patients with CD4 count > 500 cell/dL, HCC was present in those who were hepatitis C positive." (PMID 35875299, 2022).
hepatitis C (continued). "Other persistent viral infections such as Dengue and Hepatitis C have also been shown to drive the differentiation of cytotoxic CD4+ T cells with a profile that does not fit neatly into the Th1/2/9/17 paradigm." (PMID 33936035, 2021). "A characteristic example observed in chimpanzees is the failure of cytotoxic cells to control hepatitis C infection in the absence of CD4+ T cells." (PMID 31693899, 2019). "Baseline median age was 36.2 years (IQR 30.5 to 42.6), BMI 20.2 kg/m2 (IQR 18.2 to 22.4), absolute CD4 cell count 120 cells/mm3 (IQR 33 to 324) and nadir CD4 cell count 119 cells/mm3 (IQR 33 to 323); and 1408 of 199,707 (0.7%) had a history of hepatitis C infection." (PMID 30165821, 2018). "First, this was a retrospective study and we had no access to patient clinical data (cART regimens, adherence, CD4+ cell counts, HIV viral load, COPD management, active hepatitis C), which could have helped us to more completely interpret our results." (PMID 27846297, 2016). "Patients with hepatitis C did not receive interferon-α and ribavirin until their CD4+ T cell counts were higher than 350 cells/μL." (PMID 28033281, 2016). "IDU stratified results were very similar to those for hepatitis C co-infection for which, up to year six, higher median CD4+ cells counts were shown for those not reporting injection drug use and not co-infected with hepatitis C." (PMID 24695533, 2014). "These women were also less likely to have Hepatitis C. It could be hypothesized that the reason why LEE and rash were seen more frequently in women with higher baseline CD4 counts on NVP-based regimens was due to these confounding factors." (PMID 20838641, 2010). "Tetramer+ CD4+ T cells were detected in all seven patients with acute hepatitis C, irrespective of clinical outcome, with frequencies ranging from 0.007% to 0.65% (mean 0.16%+/−0.2)." (PMID 17653276, 2007). "Firstly, although the analysis was adjusted for major factors that have been shown to affect CD4+/CD8+ T-cell ratio such as age, gender, ethnicity, Hepatitis C and HIV RNA levels, some individuals may be genetically pre-disposed to high or low CD4+/CD8+ T-cell ratio." (PMID 24816636, 2014). "CD4+ T cell help is critical in maintaining antiviral immune responses and such help has been shown to be sustained in acute resolving hepatitis C. In contrast, in evolving chronic hepatitis C CD4+ T cell helper responses appear to be absent or short-lived, using functional assays." (PMID 17653276, 2007). "This hypothesis is further supported by higher levels of CD4+/CD25+/FoxP3+ Tregs in mice with severe disease, indicating that CD4+/CD25+/FoxP3+ Tregs might reduce virus-specific CD8+ T cell effector function, which has also been demonstrated for hepatitis C virus infections." (PMID 38979428, 2024). "Demographic characteristics, CD4 cell count and HIV viral load of patients' referred and non-referred for hepatitis C treatment consideration." (PMID 25036553, 2014). "In conclusion, using a novel HLA-DR1 tetramer complexed with an immunodominant CD4+ T cell epitope, we could show that HCV specific CD4+ T cells are induced in each patient with acute hepatitis C irrespective of outcome." (PMID 17653276, 2007).
Insulin resistance (111 papers, 2009 to 2026). Increased resistance towards insulin, that is, diminished effectiveness of insulin in reducing blood glucose levels. "In obese children, increased production of IFN-γ secreted from CD4+ T cells was associated with insulin resistance and NASH." (PMID 36552805, 2022). "In this study of well-treated PLWH, abdominal obesity, BMI ≥ 25, exposure to older generation ART, and CD4+ nadir < 200 cells/μL was associated with insulin resistance." (PMID 35643429, 2022). "The association of nadir CD4 count with future insulin resistance and mitochondrial dysfunction has been observed in CPHIV." (PMID 34972147, 2021). "MHCII-deficient mice are protected from HFD-induced insulin resistance with the reduction of ATMs and CD4+ T cells accumulation in VAT." (PMID 30233575, 2018). "Our study found an association between low CD4 percent and MO increase and, in turn MO increase and increase in insulin resistance." (PMID 24587328, 2014). "In our study, higher levels of tPAI-1 were associated with lower CD4 percent and predicted insulin resistance in an adjusted model." (PMID 24587328, 2014). "An emerging tool for assessing the impact of T2DM on immune aging in PLWH is the triglyceride–glucose (TyG) index, a surrogate marker of insulin resistance associated with reduced CD4/CD8 ratio, increased frequencies of senescent CD8+ T cells, and greater clinical frailty." (PMID 41153793, 2025). "In adipose tissue from high-fat diet-fed mice, CD153+ CD4+ T cells also expressed Spp1 (encoding osteopontin), which may contribute to insulin resistance through osteopontin production." (PMID 40534878, 2025). "An alternative pathway could involve reduced albumin levels (associated with lower CD4 counts in the non‐pregnant population), given the link between high albumin levels and insulin resistance." (PMID 37012900, 2023). "In addition to older generation ART, CD4+ nadir < 200 cells/μL was associated with insulin resistance." (PMID 35643429, 2022). "To determine whether the decrease in the Treg fraction mediates COX-2 deficiency–induced insulin resistance, we adoptively transferred CD4+Foxp3+ Tregs from Foxp3-eGFP mice into either COX-2–KO mice or control littermates." (PMID 35260536, 2022). "Moreover, depletion of CD8 memory T lymphocytes is observed, together with a decreased number and function of CD4+ T lymphocytes and increased number of regulatory T cells (Treg), possibly caused by leptin and insulin resistance." (PMID 35062740, 2022). "Another study revealed that after adoptive transfer into obese Rag1-null mice, CD4+ T cells gained a Th2 profile, indicated by the production of IL-4 and IL-13, which was associated with reversal of enhanced weight gain and insulin resistance in recipient obese Rag1-null mice." (PMID 30459770, 2018). "We could previously show that mice fed with high fat diet (HFD) develop systemic insulin resistance (IR) and glucose intolerance (GI) associated with CD4-positive T-lymphocyte infiltration into visceral AT." (PMID 20955583, 2010). "In T2D, CD4+ T cells participate in the pathology of insulin resistance, which relates to chronic inflammation." (PMID 39397795, 2024). "This study posits PD-1+ CD4 Tconv cells as potential mediators of insulin resistance within insulin-sensitive tissues, substantiated by evidence from a diverse range of patient cohorts." (PMID 38380252, 2024). "This reduction in CD4+ T cells potentially undermines the body’s ability to control inflammation, exacerbating insulin resistance and beta-cell dysfunction." (PMID 39877357, 2024). "Currently, computational models have been used to study some of the associated effects of insulin resistance on some of the constituent cells of VAT, such as CD4+ T lymphocytes." (PMID 37026009, 2023). "For this reason, we suspect that there is a huge difference in gene expression between CD4+ CD52low T cells and CD4+ CD52high T cells, and this difference is likely to be related to insulin resistance and T2DM." (PMID 33705353, 2021).
Insulin resistance (continued). "Further investigation is required to determine if CD3+CD4+/CD3+CD8+ ratio is able to act as immune indicators of insulin resistance and islet β-cell function in RPL patients." (PMID 33935964, 2021). "The TNF in CD4 T cells was unchanged relative to the control group in the insulin resistance study, whereas the TNF from CD8+ T cells was more abundant in the BpOmpW group compared to control cells (p = 0.012)." (PMID 34966388, 2021). "Taken together, these data indicate that the differentiation and activation state of CD4+ and CD8+ T cells is strongly associated with insulin resistance." (PMID 33349270, 2020). "In the insulin resistance control group, the expression levels of IL-6, RORγt, and IL-17 increased, whereas those of IL-10, FoxP3, and CD4+CD25+Treg decreased." (PMID 31218568, 2019). "CD4+ Treg cells protect against tissue inflammation and insulin resistance, and are less frequent in obese adipose tissue compared to lean." (PMID 30559739, 2018). "In mice fed HFD, depletion of perforin causes aggravated adiposity and insulin resistance, together with upregulation of IFN-γ-producing CD4+ and CD8+ T cells as well as M1 macrophages in VAT." (PMID 30459770, 2018). "Less evidence is available in the clinical setting, but insulin resistance in obese humans has been shown to be linked to elevated IgG autoantibodies and immune cell accumulation in VAT, in particular, activated CD4+ and CD8+ T cells." (PMID 28891325, 2018). "In this study, we elucidated the role of CD4+CD25+Foxp3+ Tregs to insulin resistance in a CBA/J mice model of HT is established by the administration of iodine and induction of immune response to thyroid globulin." (PMID 29541033, 2018). "During obesity and other metabolic challenges, these cells are overwhelmed by proinflammatory CD8+ cells and Th1 CD4+ cells, which promote insulin resistance and glucose intolerance." (PMID 28891325, 2018). "Inhibition of MHCII expression in adipocytes by adrenomedullin 2 treatment restores the HFD-induced early insulin resistance due to decreased CD4+ T cell activation." (PMID 30233575, 2018). "Levels of tPAI-1 increase as CD4 percent decreases and predict insulin resistance in an adjusted model." (PMID 24587328, 2014). "Included among these biomarkers was tPAI-1 which also correlated inversely with CD4 percent, positively with MO levels, and predicted insulin resistance." (PMID 24587328, 2014). "In contrast, consistent with our findings on the putative importance of visceral adipose tissue CD4+Foxp3+ T cells in insulin resistance, the proportions were similar in the SC WAT depot in both genotypes." (PMID 23562076, 2013). "Multivariate analyses identified five factors associated with severe fibrosis (F3–F4): increasing age, insulin resistance (HOMA ≥3.8), past alcohol consumption, duration of HIV infection of ≥10 years and a nadir CD4-cell count of <200/mm3." (PMID 23226258, 2012). "In our study, FMR as a continuum was significantly associated with insulin resistance evaluated by HOMA, even after adjustment for gender, age, IP, NRTI, NNRTI, CD4 cell count and HIV RNA viral load." (PMID 22866963, 2012). "Induction of CD4+LAP+ Tregs by oral CD3 antibody as well as adoptive transfer of CD4+LAP+ Tregs resulted in amelioration of markers of insulin resistance in ob/ob mice." (PMID 21298111, 2011). "The abnormal differentiation of CD4+ Th cell subpopulations may impair β-cell function, aggravate insulin resistance, and contribute to the development of T2D through producing cytokines and participating in chronic and low-grade inflammation." (PMID 39397795, 2024). "Furthermore, the complex pathogenesis of SLD includes gut dysbiosis, insulin resistance, metabolic and fat tissue dysfunction, as well as changes in cellular immunity, the neutrophil-to-lymphocyte ratio, and dysregulation of CD4 T cell function." (PMID 38337491, 2024).